FSIP2 (fibrous sheath interacting protein 2)
Description:
Plays a role in spermatogenesis.
Synonyms: FLJ34780; SPGF34
Tractability: PROTAC: ubiquitination databases record sites on it.
Gene: Protein-coding gene on chromosome 2 (185,738,804 to 185,833,290, forward strand). Ensembl gene ENSG00000188738.
Subcellular location (Human Protein Atlas): Microtubules; Basal body; Cytokinetic bridge; Mid piece; Mitotic spindle; Primary cilium
Gene Ontology:
Biological process: flagellated sperm motility; protein localization to cilium; sperm axoneme assembly
Cellular component: sperm end piece; sperm head-tail coupling apparatus; sperm midpiece; sperm principal piece
Genetic constraint (gnomAD): Loss-of-function variants: 304 observed, 427.22 expected, observed/expected ratio (o/e) 0.71, 90% interval 0.65 to 0.78. The upper end of that interval is the gene's LOEUF score, 0.78, which puts it in group 3 of 6, group 1 being the genes least tolerant of losing a copy. Missense variants: 6,950 observed, 7,461.9 expected, observed/expected ratio (o/e) 0.93, 90% interval 0.91 to 0.95. Synonymous variants: 2,385 observed, 2,620.5 expected, observed/expected ratio (o/e) 0.91, 90% interval 0.88 to 0.94.
Homologues: Orthologues: chimpanzee FSIP2 (95% identical), macaque FSIP2 (93% identical), pig FSIP2 (70% identical), rabbit FSIP2 (67% identical), dog FSIP2 (64% identical), mouse Fsip2 (59% identical), rat Fsip2 (59% identical).
Diseases named in the same sentence as FSIP2 in open-access papers:
FSIP2 is named in the same sentence as 23 diseases in open-access papers, as found by Europe PMC text mining. Sharing a sentence is not in itself a finding about the gene and the disease. The quoted sentences say what the papers report.
testicular germ cell tumor (5 papers, 2020 to 2024). A germ cell tumor arising from the testis. "Although expression of FSIP2 is testis-specific, we have found that FSIP2 has a higher mutation frequency not only in male reproductive system tumors, such as testicular germ cell tumors, but also in Paget disease, liver cancer and other cancers." (PMID 34113648, 2021). "Recurrent amplification of FSIP2 has been reported in 22% of seminomas and 15.3% of testicular germ cell tumors." (PMID 34513706, 2021).
asthenozoospermia (3 papers, 2025). "Four patients with an extreme (oligo)asthenozoospermia had one homozygous or two heterozygous pathogenic variant(s) in MMAF‐associated genes (CFAP43, CFAP69, DNAI1, and FSIP2)." (PMID 39180390, 2025). "Thus, idiopathic asthenozoospermia can be monitored through AKAP3, AKAP4, and FSIP2 within the cAMP/PKA signaling pathway." (PMID 40469444, 2025). "Mutations in FSIP2, characterized by the absence of CPC, IDA, and ODA, can cause idiopathic asthenozoospermia due to the lack of AKAP4 protein." (PMID 40469444, 2025).
breast carcinoma (3 papers, 2018 to 2022). "A higher FSIP2 mutation rate was reported in metastatic breast cancer compared to that in early stage breast cancer." (PMID 34513706, 2021). "Several studies demonstrated that FSIP2 was associated with metastasis and drug response in breast cancers; therefore, we suspected that FSIP2 mutation might contribute to the survival advantage of disseminated lesions." (PMID 35804832, 2022).
Infertility (3 papers, 2022 to 2023). "Among these mutated infertility genes, mutations of FSIP2, CFAP69, CEP19, MSH5 or MCM8 are recessive for spermatogenic failure or premature ovarian insufficiency." (PMID 35547809, 2022). "Therefore, we hypothesized that FSIP2 variants identified here may be responsible for the observed infertility phenotypes." (PMID 36632462, 2023).
clear cell renal cell carcinoma (2 papers, 2020 to 2021). "Additionally, FSIP2 shows high expression in patients with clear cell renal cell carcinoma and is associated with poor survival outcomes and prognosis." (PMID 34513706, 2021).
Skin Cutaneous Melanoma (2 papers, 2021 to 2024). "Though the role of FSIP2 in PD remains unclear, FSIP2 exhibits immunomodulatory functions in skin cutaneous melanoma." (PMID 38903536, 2024).
gastric cancer (1 paper, 2022). A primary or metastatic malignant neoplasm involving the stomach. "We also found six genes in MSS tumors (EYS, FAT4, FSIP2, PCDHA1, RAD50, and RECQL4) and two in MSI tumors (EXO1 and FSIP2) that were clonally mutated in multiple patients and have not been previously identified as drivers of gastric cancer or other cancers." (PMID 36970058, 2022).
kidney cancer (1 paper, 2020). Primary or metastatic malignant neoplasm involving the kidney. "Further, the results from the CCLE database showed that FSIP2 mRNA expression in the kidney cancer cell lines ranked 22nd among the cell lines from different cancer tissues." (PMID 33162809, 2020).
male infertility (1 paper, 2023). The inability of the male to effect fertilization of an ovum after a specified period of unprotected intercourse. "Overall, our study shows that male infertility caused by FSIP2 variants can be rescued by ICSI treatment." (PMID 36632462, 2023).
cancer (7 papers, 2014 to 2022). A tumor composed of atypical neoplastic, often pleomorphic cells that invade other tissues. "We analyzed the downloaded TCGA-SKCM queue data by Genomic Identification of Significant Targets in Cancer 2.0 (GISTIC2.0) after grouping according to the mutation status of FSIP2." (PMID 34113648, 2021). "In the 8-mRNA signature (KCNJ18, RPE65, GRIA1, LCN15, C11orf21, ANXA13, FSIP2 and KRT76), the expressions of some mRNAs have been reported to have significant associations with the survival in some cancers." (PMID 35675043, 2022). "Collectively, these results indicate that FSIP2 plays a role in metastasis, tumor invasion, and chemotherapeutic resistance in cancer." (PMID 34513706, 2021). "We explored the levels of FSIP2 mRNA transcripts in RCC using the Oncomine cancer database." (PMID 33162809, 2020). "The differential expression of FSIP2 mRNA was found to be reported in 20 human cancers." (PMID 33162809, 2020). "However, very few studies have investigated the role of FSIP2 expression in cancer." (PMID 33162809, 2020). "Similarly, CAGE1, a gene widely associated with cancer was significantly upregulated in the GFP-KDEL cells, while it was significantly downregulated in SUN1L-KDEL cells illustrating an opposite pattern of response of the gene FSIP2 to LINC disruption." (PMID 32942630, 2020). "Despite a lack of studies on the relationship between FSIP2 and cancer, FSIP2 has been shown to not only an important part of AKAP4 but to also influence the function of PKA by docking to AKAP4." (PMID 34113648, 2021).
tumor (7 papers, 2015 to 2025). "We attempted to elucidate the possible mechanism by which FSIP2 mutation and the tumor immune microenvironment affect the efficacy of ICI treatment in SKCM patients." (PMID 34113648, 2021). "However, as there are few studies or data on FSIP2 mutations and tumor immunotherapy, the association between FSIP2 mutations and SKCM needs to be verified by further experiments." (PMID 34113648, 2021). "Interestingly the tumour from patient 21, which harboured a FSIP2 amplification, also carried a missense mutation in AKAP4." (PMID 25609015, 2015). "The study also identified other genes with significant association within at least one tumor type or breed, including ASPM, which functions in the mitotic spindle, and SPEF2 and FSIP2, both related to spermatogenesis." (PMID 34344882, 2021). "It was found that FSIP2 may serve as a potential predictive biomarker for prognosis of ccRCC as it may play a role in metastasis and tumor invasion." (PMID 38715151, 2024). "In addition, GSEA of the cohort TCGA-SKCM showed that pathways related to immunosuppression and tumor progression were significantly downregulated in the FSIP2-MT group." (PMID 34113648, 2021). "Additionally, FSIP2 may play a role in metastasis, tumor invasion, and chemotherapeutic resistance and may be used as a predictive diagnostic biomarker for the prognosis of ccRCC." (PMID 33162809, 2020). "To explore the possible mechanisms, we systematically analyzed possible factors, including tumor immunogenicity (the TMB and NAL), CNV, the TME and immune-related gene expression, in the FSIP2-MT and FSIP2-WT groups." (PMID 34113648, 2021). "Our GSEA of TCGA-SKCM data also indicated that pathways related to tumor progression (MAPK and FGFR), immunomodulation, and IL-2 synthesis inhibition were significantly downregulated in the FSIP2-MT group." (PMID 34113648, 2021). "The highest ranking gene from this analysis was fibrous sheath interacting protein 2 (FSIP2) at 2q32.1, with seven recurring amplifications observed across six (15.3%) tumours." (PMID 25609015, 2015). "The pathways related to tumor progression, such as positive regulation of the MAPK cascade and FGFR (FGFR1, FGFR2, FGFR2c, FGFR3, and FGFR3c) ligand binding and activation, were significantly downregulated in the FSIP2-MT group (ES < 0, p < 0.05), suggesting a better efficacy." (PMID 34113648, 2021). "Due to tumor heterogeneity, t-test may not detect significant changes in differential expression; hence, we performed outlier analysis for FSIP2 expression." (PMID 33162809, 2020).
FSIP2 also shares sentences with these, for which no sentence is quoted: Globozoospermia (2 papers); Azoospermia (1); leprosy (1); liver cancer (1); male reproductive system tumors (1); metastatic tumors (1); oligospermia (1); Paget disease (1); Premature ovarian insufficiency (1); renal cell carcinoma (1); seminoma (1); spermatogenic failure (1).